GMEB2 (glucocorticoid modulatory element binding protein 2)
Description:
Trans-acting factor that binds to glucocorticoid modulatory elements (GME) present in the TAT (tyrosine aminotransferase) promoter and increases sensitivity to low concentrations of glucocorticoids. Also binds to the transferrin receptor promoter. Essential auxiliary factor for the replication of parvoviruses.
Synonyms: GMEB-2; KIAA1269; P79PIF; PIF79
Tractability: PROTAC: UniProt records ubiquitination sites on it; ubiquitination databases record sites on it; its protein half-life has been measured.
Gene: Protein-coding gene on chromosome 20 (63,587,601 to 63,628,426, reverse strand). Ensembl gene ENSG00000101216.
Subcellular location: Nucleus; Cytoplasm
Subcellular location (Human Protein Atlas): Nucleoplasm; Cytosol
Gene Ontology:
Molecular function: identical protein binding; protein binding; sequence-specific double-stranded DNA binding; DNA-binding transcription activator activity, RNA polymerase II-specific; DNA-binding transcription factor activity, RNA polymerase II-specific; RNA polymerase II cis-regulatory region sequence-specific DNA binding; DNA binding; sequence-specific DNA binding
Biological process: positive regulation of transcription by RNA polymerase II; transcription by RNA polymerase II
Cellular component: cytosol; nucleoplasm; chromatin; nucleus; cytoplasm
Genetic constraint (gnomAD): Loss-of-function variants: 6 observed, 32.22 expected, observed/expected ratio (o/e) 0.19, 90% interval 0.1 to 0.37. The upper end of that interval is the gene's LOEUF score, 0.37, which puts it in group 1 of 6, group 1 being the genes least tolerant of losing a copy. Missense variants: 483 observed, 572.88 expected, observed/expected ratio (o/e) 0.84, 90% interval 0.78 to 0.91. Synonymous variants: 272 observed, 255.26 expected, observed/expected ratio (o/e) 1.07, 90% interval 0.96 to 1.18.
Homologues: Orthologues: chimpanzee GMEB2 (99% identical), macaque GMEB2 (99% identical), guinea pig GMEB2 (95% identical), mouse Gmeb2 (94% identical), dog GMEB2 (92% identical), pig GMEB2 (91% identical), rabbit GMEB2 (88% identical), rat Gmeb2 (87% identical), zebrafish gmeb2 (55% identical), tropical clawed frog gmeb2 (46% identical), Caenorhabditis elegans gmeb-2 (16% identical), Caenorhabditis elegans gmeb-1 (14% identical), and 2 more. Paralogues in human: GMEB1 (36% identical).
Diseases named in the same sentence as GMEB2 in open-access papers:
GMEB2 is named in the same sentence as 8 diseases in open-access papers, as found by Europe PMC text mining. Sharing a sentence is not in itself a finding about the gene and the disease. The quoted sentences say what the papers report.
glioma (2 papers, 2021 to 2023). A benign or malignant brain and spinal cord tumor that arises from glial cells (astrocytes, oligodendrocytes, ependymal cells). "Changes in the activity of an enhancer on 20q13.33 led to abnormal expression of multiple genes associated with glioma risk (e.g., RTEL1, RTEL1-TNFRSF6B, SRMS and GMEB2)." (PMID 37349788, 2023). "We further show that this SNP affects glioma risk potentially through the altered expression of STMN3, RTEL1, GMEB2, and several other genes based on CRISPR deletion of the risk enhancer." (PMID 33169458, 2021). "Our data also implicate RTEL1 and GMEB2 in glioma, but their role may be more context‐specific." (PMID 33169458, 2021).
depression (1 paper, 2021). "Among the common genes of depression and diabetes, there are four TFs, namely, BCL3, MXI1, GMEB2, NFKB1." (PMID 34833079, 2021).
prostate carcinoma (1 paper, 2021). A carcinoma that arises from epithelial cells of the prostate gland. "GMEB2 has been associated with prostate cancer, but its role in gliomagenesis is unknown." (PMID 33169458, 2021).
tumor (2 papers, 2022 to 2025). "First, we confirmed that GMEB2 expression was higher in 12 human CRC tissues than in the matched adjacent non-tumour tissues." (PMID 36551532, 2022). "Thirty-five days after implantation, GMEB2-silenced cells had formed much smaller tumours than sh-NC cells regarding tumour volume and weight." (PMID 36551532, 2022). "The tumour tissues were sectioned and assessed by haematoxylin and eosin (H&E) staining and IHC, which verified the lower GMEB2 expression in the GMEB2-knockdown tumour group than in the sh-NC group." (PMID 36551532, 2022). "FLK4, BACH1, and GMEB2 were important regulators of C0 RPS4Y1+ tumor cells." (PMID 40230840, 2025). "GMEB2 possesses intrinsic transactivation activities, which may play significant roles in tumours." (PMID 36551532, 2022). "For further confirmation, we detected GMEB2 expression in 12 matched pairs of human CRC tissues and adjacent non-tumour tissues by qRT-PCR and 3 matched pairs of tissues by immunohistochemistry (IHC)." (PMID 36551532, 2022). "Interestingly, a recent study found a N6-methyladenosine (m6A) modification on GMEB2 mRNA, which may be recognized by the m6A reader YTHDF1 in tumour cells." (PMID 36551532, 2022).
cancer (1 paper, 2022). A tumor composed of atypical neoplastic, often pleomorphic cells that invade other tissues. "However, as a transcription factor, the role of GMEB2 in cancer is still unclear, and further studies are needed." (PMID 36551532, 2022). "Therefore, whether GMEB2 mRNA is regulated by YTHDF1 in an m6A-dependent manner in cancer deserves further investigation." (PMID 36551532, 2022). "However, there is no detailed study in cancer that has identified the role of GMEB2 as a transcription factor." (PMID 36551532, 2022). "The biological function and regulatory mechanism of GMEB2 in cancer are still not clear." (PMID 36551532, 2022).
GMEB2 also shares sentences with these, for which no sentence is quoted: colorectal cancer (1 paper); diabetes (1); psychiatric disorder (1).